PPARG (peroxisome proliferator activated receptor gamma)
Diseases named in the same sentence as PPARG in open-access papers (continued):
Sharing a sentence is not in itself a finding about the gene and the disease.
metabolic disorders (continued). "Nuclear receptors retinoic X receptor α (RXRα) and peroxisome proliferator activated receptor γ (PPARγ) function potently in metabolic diseases, and are both important targets for anti-diabetic drugs." (PMID 22140563, 2011). "PPARγ is a member of the ligand-activated nuclear receptor superfamily: its ligands act as insulin sensitizers and some are approved for the treatment of metabolic disorders in humans." (PMID 19043603, 2008). "Furthermore, propolis activates PPARα in the liver to balance lipid metabolism, and its active component, caffeic acid phenethyl ester (CAPE), can upregulate PPARα and downregulate PPARγ to relieve fat accumulation and metabolic disorders." (PMID 41141253, 2025). "Utilizing a strategy of PPARγ deacetylation may lead to the design of safer and more effective agonists of this nuclear receptor for the treatment of metabolic diseases." (PMID 40994455, 2025). "This discovery offers new insights into PPARγ biology and its regulation, and suggests that RXRγ could be a valuable target for addressing metabolic diseases." (PMID 40855678, 2025). "In addition to its role in metabolic diseases, PPARγ also plays a role in inflammation and immune responses." (PMID 41190023, 2025). "In conclusion, the hypothesis that thiamine can act as a natural PPARγ activator and a potential therapeutic agent for T2D and related metabolic disorders holds significant promise." (PMID 41368574, 2025). "Furthermore, the occurrence of metabolic disorders seems to be attributed to the elevated expression of PPARγ induced by a high-fat diet." (PMID 38167433, 2024). "Thus, future in-depth studies on the mechanisms of PPARγ+ macrophage action in human skeletal muscle specimens will provide guidance for the development of new strategies for the treatment of human metabolic diseases." (PMID 39857594, 2024). "Therefore, pharmacological PPARγ agonism is considered a promising strategy for the treatment of metabolic diseases." (PMID 38988496, 2024). "Therefore, the development of efficient and safe PPARγ modulators for the treatment of metabolic diseases is emerging." (PMID 38988496, 2024). "Elucidating the precise molecular mechanism by which SCL extract components activate ERK and subsequently reduce PPARγ may provide clues for the therapeutic manipulation of adipogenesis in metabolic diseases." (PMID 38512891, 2024). "Thus, PPARγ agonists can be used as drugs against metabolic disorders, including T2D, by improving insulin sensitivity and reducing plasma glucose concentration." (PMID 36339572, 2022). "Taken together, our data propose pharmacological reduction of LIP expression as an approach to switch the unhealthy metabolic phenotype of obese individuals into a healthy obese phenotype to prevent the development of metabolic disease (possibly together with pharmacologic PPARγ activation)." (PMID 35451956, 2022). "Previous studies indicated that supplementation with SCFAs effectively decreased the expressing level of peroxisome proliferator-activated receptor gamma (PPARγ) in mice, achieved the transformation from lipid synthesis to lipid oxidation, and alleviated the metabolic disorders induced by HFD." (PMID 35979004, 2022). "If MMPP can act as a PPARγ agonist, it can bind to and activate PPARγ; thus, it may be a candidate for modulating metabolic disorders." (PMID 36339572, 2022). "Chronic cold exposure, exercise, cyclic AMP, and PPARγ agonists are all examples of stimuli that can elicit the browning process, and scientists are actively pursuing other agents able to target this process to treat metabolic diseases." (PMID 34777009, 2021). "Taken together, L971 might contribute to regulation of metabolic disorders through direct influence of PPARγ signalling pathway or indirect interfering with JAK/STAT and NFκB signalling pathways." (PMID 34018320, 2021).
metabolic disorders (continued). "By regulating the expression of related genes, PPARG can correct liver lipid metabolism disorders, reduce oxidative stress, reduce the fibrotic cytokine α-smooth muscle actin (α-SMA) in HSCs and is essential for both adipocyte differentiation and HSC quiescence." (PMID 33510287, 2021). "PPARγ plays an important role in many metabolic diseases but its function remains controversial." (PMID 34966274, 2021). "Pioglitazone is an FDA-approved PPARγ agonist used to treat metabolic diseases, such as T2D." (PMID 34572374, 2021). "As above reported, PPARγ may be considered a novel therapeutic target to prevent the cardiac complications and HF in metabolic disorders, since PPARγ agonists exhibited beneficial action against CVD." (PMID 34679777, 2021). "It is also suggested that targeting galectin-1 may represent a new way to treat a wide spectrum of metabolic diseases by modulating PPARγ activity." (PMID 33431823, 2021). "Promising studies have shown that certain PPARγ agonists may be beneficial in treating metabolic disorders with minimal off-target effects." (PMID 32351446, 2020). "PPARγ is a pharmacological target in inflammatory and metabolic diseases." (PMID 31534496, 2019). "The demethylation of Pparγ promoter during adipocyte differentiation, as we have observed, is crucial for proper adipogenesis, and this had been reported previously; however, data concerning Pparγ promoter in metabolic disorders are contradictory as well as being tissue-specific." (PMID 31883537, 2019). "PIO and MSCs have been shown to inhibit fibrosis and PPARs have already been considered an attractive therapeutic target for the treatment of metabolic disorders and PPARγ agonists were shown to effectively attenuate oxidative stress, inflammation and apoptosis." (PMID 29959408, 2018). "By avoiding this adipogenic activity, lesinurad could help PPARγ to a rebirth as target for metabolic disorders or serve as lead compound for the development of potent drug-like sPPARγM by selective optimization of side-activities." (PMID 30202096, 2018). "Aloxe3 is, therefore, a potentially novel effector of the hepatocellular fasting response that leverages both PPARγ-mediated and pleiotropic effects to augment hepatic and whole-host metabolism, and it is, thus, a promising target to ameliorate metabolic disease." (PMID 30135298, 2018). "Targeting the ATX-LPA-LPA1-6 pathway holds therapeutic potential, as this signaling axis may promote the development of metabolic disorders through multiple mechanisms involving inflammation, fibrosis, and impaired mitochondrial function and PPARγ activation." (PMID 29570618, 2018). "In addition, weight gain as a common side-effect of PPARγ agonists is an obstacle for their use especially in metabolic diseases." (PMID 30202096, 2018). "In order to take full advantage of the collaborative action of these two critical antioxidant pathways for alleviation of ROS-induced damages in various metabolic diseases and drug-induced injury, many researchers have tried to apply several Nrf2 and PPARγ activators to various disease models." (PMID 28928902, 2017). "In support of this, partial inactivation of PPARγ in PPARγ heterozygotes was found to increase insulin sensitivity, and several pharmacological agents characterized as PPARγ antagonists were shown to ameliorate metabolic disorders." (PMID 27176632, 2016). "Modeling the human PPARγ dominant negative mutations is important due to its impact in human metabolic diseases." (PMID 27483259, 2016). "Plenty of studies have demonstrated the central role of PPARγ in metabolic diseases." (PMID 27483259, 2016). "In addition, PPARγ is reported to improve adipocytokine dysregulation in adipose tissue, including adiponectin, in metabolic disorders." (PMID 24991574, 2014). "Undoubtedly, PPARG is one of the most studied genes accounting for metabolic disorders." (PMID 24790595, 2014).
metabolic disorders (continued). "It was proposed that fine-tuning the activity of PPARα and PPARγ, in particular, by nutritional approaches at specific time/s during the transition period might be a way to prevent and/or help the cows overcome metabolic disorders." (PMID 23737762, 2013). "Due to the important functions played by the PPAR isotypes, PPARα and PPARγ have long been considered promising drug targets for human metabolic disorders as they regulate lipid and/or glucose homeostasis by controlling uptake, synthesis, storage, and clearance." (PMID 23737762, 2013). "Is PPARγ still an attractive pharmacological target to treat metabolic disease?" (PMID 22745632, 2012). "Compound 222, in contrast, was the only metabolite found to be a potent dual agonist of both PPARα and PPARγ (50 μM= 2.13-fold induction; 25 μM= 1.85-fold induction; 12.5 μM= 1.42-fold induction), and its activity represents a great potential for the treatment of metabolic disorders." (PMID 37765290, 2023). "We accordingly hypothesized that FATP and FABP act on fatty acid transport during lipid metabolism by activating PPARG through transport-related transcription factors acting on adipocytes, contribute to the prevention of various metabolic disorders, and provide energy." (PMID 35627218, 2022). "Thus, our study highlights that PPARγ agonism may be a therapeutic option for targeting NLRP3-related metabolic diseases." (PMID 33500734, 2021). "Therefore, PPARγ has been regarded as a drug target against metabolic diseases." (PMID 30463189, 2018). "Thus, the extent of PPARγ activation may produce differential effects with regard to the treatment of metabolic disorders." (PMID 27176632, 2016). "In addition to its primary role to antagonize AT1 receptor, telmisartan has unique properties which might ameliorate metabolic diseases and vascular complications via different pathway from PPARγ." (PMID 24827148, 2014). "Therefore, we postulate that effects of EWGP on metabolic disorders may be partly through the inhibition of PPARγ signaling." (PMID 23533476, 2013). "An important advance was the recent observation that the triorganotins TBT and TPT are potent activators of the nuclear hormone receptors RXR and PPARγ and that they promote adipocyte differentiation, suggesting that these organotins might contribute to the development of metabolic diseases." (PMID 18958157, 2008). "PPARγ agonists, particularly the TZD class, have long been recognized for their insulin-sensitizing and anti-inflammatory properties in metabolic diseases." (PMID 41476922, 2025). "Curcumin’s mechanism of action in metabolic disorders involves multiple pathways, including PI3K-Akt, MAPK, peroxisome proliferator-activated receptor gamma (PPAR-γ), cyclooxygenases, and SMAD proteins." (PMID 39103711, 2025). "For instance, pea protein hydrolysate alleviates GDM-related metabolic disorders and placental dysfunction by inhibiting the PI3K/AKT/mTOR/PPARγ signaling pathway." (PMID 41460830, 2025). "For example, a study demonstrated that remodeling of the ECM in adipose and muscle tissue plays a pivotal role in metabolic disease development, identifying genes such as TCF7L2, ADIPOQ, CD36, PPARG, IL6, SIRT1, and COL5A1 as key regulators of inflammation." (PMID 41303617, 2025). "Thus, the hypermethylation of PPARG itself or its target genes might directly or indirectly link PPARG with the epigenetic regulation of adipogenesis and the metabolism of mature adipocytes, including a shift towards metabolic disorders." (PMID 39595621, 2024). "Various drugs that regulate metabolic disorders have been shown to reduce blood sugar levels in diabetic rats by activating the PI3K/Akt pathway and upregulating PPARγ expression." (PMID 38774257, 2024). "Pharmacological treatment with thiazolidinediones (TZDs), classical PPARγ full agonists, regulates these PTMs, strongly reverses the unhealthy WAT remodeling, and improves metabolic disorders." (PMID 36329235, 2023).
metabolic disorders (continued). "Together, we highlight that PPM1A may represent a therapeutic target for metabolic diseases in many aspects, such as increasing anti-inflammatory responses and enhancing the secretion of insulin-sensitizing adipokines which depends on dephosphorylation of PPARγ at Ser273." (PMID 32024237, 2020). "Our study suggests potential value of combination PPARγ and GPR120 agonists to treat metabolic disease." (PMID 33108252, 2020). "Our identification of CoQ10 and its more soluble analog idebenone as partial agonists for both PPARα and PPARγ provides new insight into PPAR molecular and genetic functions, as well as promising new reagents for treating and preventing metabolic disorders." (PMID 30171034, 2018). "Moreover, with its interesting pharmacological profile, lesinurad might also hold great therapeutic potential in metabolic diseases since adipogenic effects of PPARγ activation and resulting weight gain are a major obstacle to the therapeutic exploitation of PPARγ in metabolic diseases." (PMID 30202096, 2018). "PPARα, PPARγ, and FXR agonists are used clinically to treat lipid disorders and metabolic diseases." (PMID 37427406, 2023). "Stigmasterol has shown certain potential for the treatment of metabolic diseases, but there is no report that stigmasterol can treat metabolic diseases through PPARγ." (PMID 35178098, 2022). "Minor structural variations might allow optimizing the selective PPARγ-modulatory characteristic and reduce URAT1 inhibition to generate a more potent sPPARγM for novel indications in metabolic diseases." (PMID 30202096, 2018). "PPARγ and the PPARγ coactivator (PGC)-1α, which play key roles in various metabolic disorders, are also known to be targeted by SIRT1, but the effects of telmisartan on SIRT1- and PPARγ-signaling remain unclear." (PMID 23137106, 2012). "Taken together, our study demonstrated that PMQ up-regulates adiponectin expression via a mechanism that implicates PPARγ together with TNF-α and IL-6, suggesting that PMQ might be a potential candidate for the treatment of metabolic diseases." (PMID 21734632, 2011). "Given the impact of SIRT1 on PPARγ activityand because PPARγ activity helps determine age-related insulinresistance, SIRT1 may have animportant role in metabolic diseases and link the effects of food consumptionto body fat mass and diseases of aging." (PMID 18317516, 2007). "Our results suggest that Gnetin C may promote APN multimerization not only through activation of the PPARγ-DsbA-L-Ero-1α axis in adipose tissue but also indirectly via the Sirt1-FGF21 axis in the liver, highlighting its promise as a novel agent for metabolic disease therapy." (PMID 41290813, 2025). "Given that Cushing is a metabolic disorder, our established in vitro models may not encompass all the necessary elements to comprehensively investigate the therapeutic effects of PPARG pathway." (PMID 38098864, 2023). "Partial or non-TZD PPARγ agonism may reduce side effects while treating metabolic disorders with PPARγ activators." (PMID 37435495, 2023). "Next, we aimed to investigate whether or not the metabolic disorders induced by HFD in PPARγ3RA/+ mice could be reversed by increasing the transcriptional activity of PPARγ." (PMID 32973516, 2020). "However, whether other transcriptional factors, such as PPARγ and ERRγ, are involved in PGC-1β induced metabolic disorder in the diabetic heart need further study." (PMID 30635067, 2019). "Notably, PPARG and PPARGC1A were central activated upstream regulators in VAT vs. SAT of NK cows, thus implying that, like in humans, PPARG agonism might be a potential therapeutic target for metabolic disorders in dairy cows." (PMID 40599780, 2025). "Hence, preservation of BAT, and insulin sensitivity in BAT and residual WAT, may at least partly explain why Ad-B2(−/−) mice do not develop the overt metabolic disease seen in PPARγ-FKO and IR-FKO mice." (PMID 29459250, 2018).
metabolic disorders (continued). "Although not a PPAR ligand, DHEA stimulates PPARγ in rodents, and PPAR activation has a number of beneficial effects in rodent models of inflammation and metabolic disease." (PMID 21042414, 2010). "As a result, both knockdown of PPARγ alone as well as ICI 182780 alone can significantly alleviate BPA-induced lipid accumulation and glucose metabolism abnormalities, but neither can completely reverse the metabolic disorders." (PMID 32623698, 2021). "Pyrosequencing analyses were performed for the candidate genes KCNJ11, PPARγ, PDK4, KCNQ1, SCD1, PDX1, FTO and PEG3 in peripheral blood leukocytes (PBLs) from 25 patients diagnosed with only T2D, 9 patients diagnosed with T2D and MetS and 11 control subjects without any metabolic disorders." (PMID 28727822, 2017).